TLR2 (toll like receptor 2)
Diseases named in the same sentence as TLR2 in open-access papers (continued):
Sharing a sentence is not in itself a finding about the gene and the disease.
cancer (continued). "For TLR2 to be developed as a therapeutic target for cancers, its role in oncogenesis needs to be further elucidated." (PMID 35205112, 2022). "TLR2 has been reported to have very broad functions in infectious diseases and also in other diseases, such as chronic and acute inflammatory diseases, cancers, and even metabolic disorders." (PMID 35205112, 2022). "Through further analysis, we found that TYROBP, FCGR2B, TYROBP, LY86, and TLR2 genes were highly expressed in ccRCC carcinoma tissues." (PMID 36595751, 2022). "The role of TLR2 in cancer appears complex, confounded in part by redundancy of the multiple TLRs and the diversity of cell types expressing them." (PMID 34638266, 2021). "We demonstrate that TLR2 neutralisation efficiently blocks the inflammatory effects of TLR2 in these systems, revealing the therapeutic potential of TLR2 targeting to limit oesophageal disease and cancer progression." (PMID 33922955, 2021). "Multiple gRNAs targeting TLR2 pathway genes were enriched in cell populations selected for altered PDL1 expression, suggesting a role for cancer cell-intrinsic TLR2 in PDL1 regulation." (PMID 34638266, 2021). "Our results are thus reminiscent of a previous report on similar time-dependent regulation of HE4 expression via TLR2 mediated pathway including NF-κB signaling in cancer cells." (PMID 34054511, 2021). "In summary, accumulating data reveal the multifaceted contributions of cell surface TLR, especially TLR2, to a cancer cell-friendly microenvironment by acting on stromal and carcinoma cells with a profound impact on the quality of inflammation." (PMID 35048056, 2021). "Studies in other cancers have demonstrated both pro- and anti-tumorigenic roles of TLR2 and other TLRs." (PMID 34638266, 2021). "The available data indicate that Morgana binds directly to TLR2, while it requires additional components, present in the cancer cell conditioned medium, to bind to LRP1." (PMID 34722515, 2021). "Three agents with TLR agonist activity have been approved by the FDA for cancer treatments including bacillus Calmette-Guerin (TLR2&4 agonists mixture), monophosphoryl lipid A (TLR2/4 agonists mixture), and imiquimod (TLR7 agonist)." (PMID 34959344, 2021). "TLR2 has been demonstrated to affect cancer cell behaviors by activating several downstream signaling pathways, including NF-kB, PI3K/Akt and Wnt/β-catenin pathways." (PMID 33614649, 2021). "In particular, reduced HMGB1 activates autophagy, while its oxidized form induces apoptosis in neoplastic cells, suggesting that the HMGB1/TLR2 axis would be particularly active in promoting cancer growth in a reducing microenvironment." (PMID 33321934, 2020). "This information will contribute to the scientific debate on the use of TLR2 agonists or antagonists in cancer treatment and pave the way for new therapeutic avenues." (PMID 33321934, 2020). "Lipoimmunogens can be developed as pharmaceutical lipoproteins for cancer immunotherapy to target DCs via toll-like receptor 2 (TLR2) signaling." (PMID 32231003, 2020). "In prostate cancer, TLR2 is expressed on cancer cells and mediates the pro-tumorigenic effects induced by some pathogens such as Trichomonas vaginalis and Mycoplasma through the induction of IL-6 and IL-8 production and consequent stimulation of EMT." (PMID 33321934, 2020). "For example, TLR2 induces a cancer cell-intrinsic stimulation of the proliferation of hepatocarcinoma cells in an infection-associated mouse model." (PMID 33321934, 2020). "TLR2 activation is critical for initiating and shaping both early innate and sustained adaptive immune responses in multiple contexts including infectious diseases, cancer and TLR2‐mediated immunotherapy." (PMID 32696994, 2020). "Among these PRRs, Toll-Like receptors (TLRs) have been the most studied, with 6 gathering a significant interest in cancer vaccines, namely TLR-2, -3, -4, -7/-8, and -9." (PMID 32117911, 2020).
cancer (continued). "In this review, we discuss the divergent effects induced by TLR2 activation in different immune cell populations, cancer cells, and cancer stem cells." (PMID 33321934, 2020). "In fact, in the TME, cancer cells promote TLR2 activation in DCs, which induces the secretion of elevated levels of cytokines including IL-6 and IL-10 and the overexpression of their receptors." (PMID 33321934, 2020). "The majority of the papers analyzing the role of TLR2 in cancer progression were focused on the TLR2 cancer cell-intrinsic role and did not extensively investigate the role of TLR2 in the non-immune TME." (PMID 33321934, 2020). "For this ability to activate immune responses, TLR2 has been considered a player in anti-cancer immunity." (PMID 33321934, 2020). "The pro-metastatic activity of TLR2 is confirmed by the fact that TLR2 knockout mice develop fewer lung, liver, and adrenal metastases following the subcutaneous implantation of cancer cells as compared to their wild-type counterpart." (PMID 33321934, 2020). "This would represent a fundamental information for the development of TLR2-targeting anti-cancer therapies." (PMID 33321934, 2020). "TLR2 is a key regulator of the innate immune response and has been shown to play an important role in cancer." (PMID 32256204, 2020). "In this paper, we will review the controversial role played by TLR2 in cancer progression and discuss the possibility of TLR2 targeting for the development of more effective anti-cancer combined treatments." (PMID 33321934, 2020). "In mice, carcinoma induces activation of myeloid cells via TLR2 to stimulate lung metastasis with expression of TNF-α." (PMID 32547964, 2020). "We demonstrated that EGT was an anti-oxidant that improved cancer immunotherapy using TLR2/6 ligand in vivo." (PMID 31019508, 2019). "As a member of toll-like receptors family, TLR2 has been shown to mediate cancer metastasis by generating an inflammatory microenvironment hospitable for metastatic growth." (PMID 31675995, 2019). "Consistently, HMGB1 promoted CD133− cancer cells sphere forming ability was also abrogated following suppress the expression and function of TLR2." (PMID 31558702, 2019). "Co-IP assay further confirmed the interaction between HMGB1 and TLR2 when CD133− cancer cells were cocultured with the 250 ng/ml rhHMGB1." (PMID 31558702, 2019). "HMGB1/TLR4 or/TLR2 axes contribute to regulate inflammation during lung and liver injury, epilepsy, cancer, and heart disease." (PMID 30306212, 2019). "Pam2CSK4, a ligand of the TLR2/6 heterodimer, was used as an adjuvant for a cancer vaccine in combination with TAA (OVA in this case)." (PMID 31019508, 2019). "More interestingly, neutralizing antibodies of TLR2 and TLR4 significantly blocked NET-induced cancer cell migration, suggesting the involvement of TLR2 and TLR4." (PMID 31034495, 2019). "Among these, ‘proteoglycans in cancer’ (P = 0.0040) and ‘NF-kappa B signaling pathway’ (P = 0.0316), involving TLR2, TLR4 and IL-12B genes, were our main focus due to their roles in immunity response." (PMID 31337442, 2019). "It draws attention to TLR2, 4, and 5, which are normally expressed on cell membrane, but upon transformation toward dysplasia and cancer their expression increases and becomes more cytoplasmic." (PMID 31695691, 2019). "Emodin, which has been isolated from rhizomes of Rheum palmatum, inhibits several target molecules in inflammation and cancer, such as NF-κB and the serine/threonine kinase Akt, both important molecules in TLR2 and TLR4 signaling pathways." (PMID 30307962, 2018). "Our study adds important insights to the increasing body of literature that identifies a unique role for TLR2 in inflammation and cancer." (PMID 29467931, 2018). "The detection of higher frequencies of the TLR2, TLR4 and/or TLR9 polymorphisms in CRC patients compared with the control groups highlight the role of these polymorphism in CRC development and cancer progression." (PMID 29883450, 2018).
cancer (continued). "Based on previous experiments performed in our lab, we chose to stimulate the BMDMs with IFN-γ and TLR2/1 agonist Pam3 because this combination leads to efficient inhibition of cancer cell growth." (PMID 29276511, 2017). "TLR2, -4, and -9 was detected in cytospin preparations of all three examined cancer cell lines (PaCaDD135, MIAPaCa-2 and BxPC-3 cells)." (PMID 27941651, 2016). "In BxPC-3 and MIAPaCa-2 cancer cells TLR2 and -9 expression clearly dominated (BxPC-3: TLR2 42.9%, TLR4 2.9%, and TLR9 43.8%; MIAPaCa-2 TLR2: 40.2%, TLR4 8.5%, and TLR9 88.5%) (top and center)." (PMID 27941651, 2016). "While mycobacterial infection was previously shown to induce TLR2-NOTCH1-PI3K-mTOR-NF-κB pathway to regulate immune responses, different cancer studies have implicated NOTCH3-dependent MSI1 expression and MSI1-dependent NOTCH activation." (PMID 27532872, 2016). "In our functional analysis, we observed increased phosphorylation of Erk after treatment with all TLR agonists for TLR2, -4, and -9 (except only one cancer cell line for TLR2 activation), strongly indicating activation of the MAPK signaling pathway." (PMID 27941651, 2016). "TLR2 mRNA was present on LPS stimulated cancer cells as well as on resting and stimulated lymphocytes." (PMID 24390484, 2014). "The downstream molecule affected by TLR-2 signaling is NF-κB and NF-κB is involved in regulation of many physiological and pathophysiological processes including inflammation and cancer." (PMID 24950067, 2014). "In cancer tissue, the expressions of TLRs (e.g., TLR2) varied in different cell types (mucosa and lymphocytes)." (PMID 25547486, 2014). "From this experiment we observed a limited reduction of the cell number at the time of vaccination in presence of TLR2 vaccination that is reflected in a reduction of cancer cells in particular TCs." (PMID 23734974, 2013). "The aim of this study was to assess the association between TLR2 and TLR4 polymorphisms and cancer risk in a meta-analysis with eligible published studies." (PMID 24376595, 2013). "In this meta-analysis of 34 independent publications, we found that three genetic variants of TLRs (TLR2 −196 to −174 del, TLR4 rs4986790 and rs4986791) were significantly associated with an increased risk of overall cancers." (PMID 24376595, 2013). "This meta-analysis presented additional evidence for the association between TLR2 and TLR4 polymorphisms and cancer risk." (PMID 24376595, 2013). "It’s well known that TLR2, 4, 5 and 9 are involved in H. pylori recognition and NF-κB is a key molecule in inflammation-cancer link." (PMID 23613822, 2013). "Recently, numerous studies have investigated the associations between TLR2 −196 to −174 del and two SNPs of TLR4 (rs4986790 and rs4986791) and the susceptibility to different types of cancer; however, the results remain conflicting." (PMID 24376595, 2013). "We additionally aimed to investigate the biological effect of TLR2 on cell growth and survival, and to assess its potential in the field of cancer therapy." (PMID 22815694, 2012). "The Bacillus Calmette-Guerin-cell wall skeleton (BCG-CWS) is a TLR2 agonist and has been used as an effective adjuvant for cancer for almost 40 years." (PMID 21533081, 2011). "In that study, they further showed that ligation of TLR2 by versican elicits the production of proinflammatory cytokines, providing a positive link between inflammation and cancer metastasis." (PMID 24212952, 2011). "PGN-SA induced phosphorylation of TAK1 and IκB in the TLR2-NF-κB pathway of the cancer cells and stimulated IL-6 and TGF-β secretion in MDA-MB-231 cells." (PMID 20520770, 2010). "There is emerging data on the importance of individual components that comprise innate immunity and their relationship to IBD and cancer, however there is a paucity of information on the role of TLR2." (PMID 20885960, 2010).
cancer (continued). "TLR-2 agonists can activate innate immune cells and thus are attracting increasing attention as prophylactic and/or therapeutic agents against infectious diseases or in cancer immunotherapy." (PMID 41853276, 2026). "Notably, the co-chaperone of eHsp90, Morgana, which is secreted via unconventional pathways, enhances cancer cell motility via TLR2, TLR4, and LRP1 signaling." (PMID 41226319, 2025). "Thus, our data establish a novel cancer-induced functional connection between TLR2 and MerTK receptors on MΦ." (PMID 39941817, 2025). "Cancer-secreted Hsp70 triggered immunosuppression through TLR2-dependent upregulation of MerTK receptors and may require an Hsp70-TLR2-MerTK interaction." (PMID 39941817, 2025). "Similarly, Toll-like receptors (TLRs), particularly TLR1, TLR2 and TLR4, have been implicated in cancer development by modulating the tumor microenvironment and promoting inflammatory responses." (PMID 41254241, 2025). "The lipidation process is essential for TLR2 recognition and the activation of robust immune responses, positioning lipidated bacterial proteins as potent immunomodulators and adjuvants for vaccines against bacterial-, viral-, and cancer-related antigens." (PMID 39852815, 2025). "Furthermore, our findings revealed that cancer cells expressing high levels of TLR2 and FADD are particularly sensitive to ICD induction by UNE-C1." (PMID 39669578, 2024). "Like TLR-4, activation of TLR-2 leads to the production of pro-inflammatory cytokines that may support cancer processes." (PMID 39273213, 2024). "Furthermore, analysis of transcriptomic data from the CCLE revealed that FADD, a critical mediator in the TLR2-induced apoptosis pathway, was enriched in cancer cells sensitive to UNE-C1." (PMID 39669578, 2024). "Additionally, it has been shown that the release of HMGB1 induced by doxorubicin activates TLR2 signaling in cancer cells, contributing to a chemotherapy-resistant phenotype." (PMID 38903515, 2024). "Moreover, TLR2 was found to promote cancer stem cell self-renewal, as evidenced by studies utilizing TLR2 knockout mouse models, which demonstrated that TLR2 is crucial for cancer stem cell maintenance and the induction of regulatory T cells." (PMID 38903515, 2024). "Our previous studies also showed an essential role of TLR2 in the progression of this cancer." (PMID 39273213, 2024). "In our study, we investigated whether UNE-C1 induces ICD through TLR2 signaling in cancer cells, beyond the antigen presenting cell (APC) activation demonstrated in previous studies." (PMID 39669578, 2024). "Hence, we can classify TLR2’s protumoral effects into two primary categories: cancer cell-intrinsic and -extrinsic." (PMID 38203626, 2023). "The cancer cells in TLR2−/− mice were remained epithelioid phenotype while in TLR4−/− mice, PepO could effectively inhibit the EMT." (PMID 37925462, 2023). "TLR2 serves also as a sensor of PAMPs, representing a bridge between eukaryotic cells and the microbial world, whose alterations may influence cancer development in different ways." (PMID 38203626, 2023). "Beyond its direct effects on cancer cells, TLR2 may also confer protection from CD8+ T cell killing." (PMID 38203626, 2023). "Messaritacis et al28 hypothesized that the presence of TLR2, TLR4, and TLR9 variants affected gut homeostasis resulting in impairment of TLRs activation, thus leading to inflammation and cancer development and progression." (PMID 37404119, 2023). "Moreover, HA can form a triple complex with CD44 and TLR2 to promote the invasiveness and pro-inflammatory environment in cancer cells." (PMID 37234812, 2023). "As a result, quercetin’s anti-inflammatory and anti-apoptotic properties play an important role in cancer prevention by modulating the TLR-2 (toll-like receptor-2) and JAK-2/STAT-3 pathways and significantly inhibiting STAT-3 tyrosine phosphorylation within the inflammatory cells." (PMID 36233051, 2022).
cancer (continued). "The activation of TLR2 has been demonstrated to be supportive in anti-cancer immunity." (PMID 35205112, 2022). "In our study, TLR2 was highly expressed in most cancer types." (PMID 35937402, 2022). "As an activator of the cancer-immunity cycle, high mobility group box 1 is released simultaneously with cancer antigens to act on TLR2 and TLR4 of DCs to promote DC maturation and induce antitumor immune responses when cancer cells cause immunogenic cell death." (PMID 34071550, 2021). "Toll-like receptor 2 and 3 (TLR2/3), which abundantly expressed on human and murine DCs 22, are PRRs that recognize lipopolysaccharide and lipopeptide, and agonists of them are widely used as adjuvants in cancer vaccines." (PMID 34158858, 2021). "CARS could be secreted from cancer cells to activate immune responses via specific interactions with TLR2/6 of dendritic cells." (PMID 34178024, 2021). "While some TLRs may be procarcinogenic, such as TLR2-MyD88, others may play a protective role, inhibiting growth of cancer cells and having potent antitumoural activity, such as TLR5." (PMID 33716996, 2021). "The researchers found that HSP70 exposed on the membrane of cancer cell-generated exosomes interacts with Toll-like receptor 2 (TLR2) on the surface of myeloid-derived suppressive cells (MDSC), thereby activating the latter and protecting cancer cells from immune recognition/attack." (PMID 34943954, 2021). "Overall, these observations suggest that Barrett’s dysplasia and early-stage EAC cells have pro-inflammatory responses to TLR2 stimulation, which may be important during cancer progression." (PMID 33922955, 2021). "So far, the best characterized PRR in carcinoma cells are TLR2 and TLR4." (PMID 35048056, 2021). "However, cell-intrinsic benefits of TLR2 activity have also been described in carcinomas of the intestine, breast and liver, ovary, and OSCC." (PMID 35048056, 2021). "Several recent studies support a role for TLR2 in promoting tumorigenesis, although the mechanisms involved in its regulation may differ among cancers." (PMID 33321934, 2020). "In ovarian cancer, the cancer cell-derived exosomes could trigger inflammatory responses to go against cancer via the TLR2 and TLR4 signaling pathways." (PMID 32565722, 2020). "Since TLR polymorphisms have been associated with changes in susceptibility to many diseases, including cancers and TLRs promote the survival of cancer cells, we also correlated the coexistence of previously genotyped TLR (TLR2, TLR4 and TLR9) polymorphisms with the VDR polymorphisms." (PMID 32471257, 2020). "Indeed, normal mucosal cells display a polarization of TLR2 expression in the basolateral membrane, whereas cancer cells display a diffuse TLR2 expression in the basolateral and apical membrane, as well in the cytoplasm." (PMID 33321934, 2020). "Further studies are needed to verify whether the PAMP/DAMP/TLR2 axis may represent a safe and effective target for cancer treatment." (PMID 33321934, 2020). "Therefore, in this review, we have summarized and discussed what is currently known in the field, providing the reader with a comprehensive analysis of the pro- and anti-cancer activities played by TLR2." (PMID 33321934, 2020). "Thus, TLR2 represents a double-edge sword, whose role in cancer needs to be carefully understood for the setup of effective therapies." (PMID 33321934, 2020). "Indeed, accumulating data are suggesting that TLR2 activation induced by many current anti-cancer therapies that mediate the release of DAMPs or alterations in PAMPs present in the microbiota is detrimental for patient outcome." (PMID 33321934, 2020). "Of note, the HMGB1/TLR2 signaling pathway may trigger a positive feedback loop that fosters cancer resistance to multiple treatments." (PMID 33321934, 2020).